EPG5 (ectopic P-granules 5 autophagy tethering factor)
Description:
Involved in autophagy. May play a role in a late step of autophagy, such as clearance of autophagosomal cargo. Plays a key role in innate and adaptive immune response triggered by unmethylated cytidine-phosphate-guanosine (CpG) dinucleotides from pathogens, and mediated by the nucleotide-sensing receptor TLR9. It is necessary for the translocation of CpG dinucleotides from early endosomes to late endosomes and lysosomes, where TLR9 is located.
Synonyms: KIAA1632; hEPG5; HEEW1; NEDPAM; VICIS
Tractability: PROTAC: ubiquitination databases record sites on it; its protein half-life has been measured.
Gene: Protein-coding gene on chromosome 18 (45,800,581 to 45,967,340, reverse strand). Ensembl gene ENSG00000152223.
Subcellular location: Cytoplasm, perinuclear region; Lysosome
Subcellular location (Human Protein Atlas): Nuclear speckles
Gene Ontology:
Molecular function: protein binding
Biological process: cellular response to dsDNA; endosome to lysosome transport; nucleotide transport; toll-like receptor 9 signaling pathway; autophagosome maturation
Cellular component: lysosome; perinuclear region of cytoplasm; cytoplasm
Genetic constraint (gnomAD): Loss-of-function variants: 133 observed, 264.84 expected, observed/expected ratio (o/e) 0.5, 90% interval 0.44 to 0.58. The upper end of that interval is the gene's LOEUF score, 0.58, which puts it in group 2 of 6, group 1 being the genes least tolerant of losing a copy. Missense variants: 2,735 observed, 2,997.1 expected, observed/expected ratio (o/e) 0.91, 90% interval 0.88 to 0.94. Synonymous variants: 1,098 observed, 1,111 expected, observed/expected ratio (o/e) 0.99, 90% interval 0.94 to 1.04.
Gene-disease validity (ClinGen):
ClinGen rates the evidence that EPG5 causes each of these diseases.
Vici syndrome (autosomal recessive): Definitive. A very rare and severe congenital multisystem disorder characterized by the principal features of agenesis of the corpus callosum, cataracts, oculocutaneous hypopigmentation, cardiomyopathy and combined immunodeficiency.
Homologues: Orthologues: chimpanzee EPG5 (99% identical), macaque EPG5 (98% identical), dog EPG5 (90% identical), pig EPG5 (89% identical), rabbit EPG5 (88% identical), guinea pig EPG5 (88% identical), rat Epg5 (84% identical), mouse Epg5 (84% identical), tropical clawed frog epg5 (62% identical), zebrafish epg5 (56% identical), Drosophila melanogaster Epg5 (20% identical). Paralogues in human: LIX1L (4% identical), LIX1 (3% identical).
Diseases named in the same sentence as EPG5 in open-access papers:
EPG5 is named in the same sentence as 71 diseases in open-access papers, as found by Europe PMC text mining. Sharing a sentence is not in itself a finding about the gene and the disease. The quoted sentences say what the papers report.
Vici syndrome (35 papers, 2014 to 2026). "Mutations in EPG5 among patients with Vici Syndrome lead to impaired autophagic flux and accumulation of autophagosomes due to impaired lysosomal-autophagosome fusion." (PMID 41277110, 2026). "Vici syndrome is a severe multisystem disorder caused by recessive mutations in the EPG5 gene, which impairs autophagy by disrupting the fusion of autophagosomes with lysosomes." (PMID 41277110, 2026). "Impaired autophagy associated with pathogenic variants in EPG5 causes a rare devastating multisystem disorder known as Vici syndrome, which features neurodevelopmental defects, severe progressive neurodegeneration and immunodeficiency." (PMID 42191733, 2026). "Mutations in EPG5 are primarily associated with Vici syndrome, a multi-organ system disorder with phenotypes including cardiomyopathy, hypopigmentation, cataracts, immunodeficiency, and callosal agenesis (i.e. malformation of the corpus callosum)." (PMID 41277110, 2026). "Recessive truncating variants in the autophagy gene EPG5 have been associated with Vici syndrome, a severe early‐onset neurodevelopmental disorder with extensive multisystem involvement." (PMID 41053928, 2025). "Genetic testing identified homozygous mutations in the EPG5 gene, confirming the diagnosis of Vici syndrome." (PMID 40161923, 2025). "Human genetic studies showed that recessive mutations in EPG5 cause Vici syndrome, a multisystem disorder characterized by agenesis of the corpus callosum, hypopigmentation, myopathy, and combined immunodeficiency." (PMID 40152605, 2025). "In the same year as EPG5‐related Vici syndrome, biallelic variants in the WD repeat domain 45 gene (WDR45) were identified in patients with beta‐propeller protein‐associated neurodegeneration with brain iron accumulation." (PMID 39420677, 2025). "Epg5-deficient mice display some features of Vici syndrome, including corpus callosum changes and myopathy." (PMID 40152605, 2025). "The development and progression of Vici syndrome in human patients and mice are associated with the loss of functional EPG5 and disturbances in autophagosome–lysosome fusion and defective autophagy." (PMID 38534345, 2024). "Truncation of the EPG5 protein by recessive mutations in the human EPG5 gene results in Vici syndrome, an early-onset neurodevelopmental disorder encompassing cardiomyopathy, hypopigmentation, and immunodeficiency." (PMID 38534345, 2024). "Other patients with mutations in autophagy-related genes (e.g LRBA, TTP2 and EPG5 in Vici syndrome) show variable immune system abnormalities." (PMID 37614038, 2024). "EPG5 deficiency is associated with a wide spectrum from neurodevelopmental disorders and seizures to Vici syndrome with multi-system features including neurodevelopmental disorders, movement disorders, epilepsy, and immunodeficiency." (PMID 37895210, 2023). "EPG5 has been implicated in autolysosome formation, and muscle biopsies and fibroblasts from Vici syndrome patients reveal a severe defect in autophagosomal clearance, resulting in the failed delivery of autophagic cargo to lysosomes." (PMID 36766820, 2023). "An Epg5-deficient mouse model that partially recaptured the features of Vici syndrome exhibited elevated baseline innate immune cellular and cytokine-based lung inflammation and was resistant to lethal influenza virus infection." (PMID 35273506, 2022). "EPG5, the protein mutated in Vici syndrome, is an example of a RAB7 effector directly involved in autophagy." (PMID 34130600, 2022). "A skeletal myopathy is consistently associated with EPG5-related Vici syndrome and is evidenced by variable degrees of hypotonia and weakness, and mild creatine kinase elevations." (PMID 34130600, 2022). "Vici syndrome was initially reported in 1988 by Dionisi-Vici and colleagues in two brothers and subsequently attributed to recessive mutations in EPG5." (PMID 34130600, 2022).
Vici syndrome (continued). "Clinically, recessive mutations in the EPG5 gene are causally associated with Vici syndrome, a multisystem disorder with abnormal autophagy and varying degrees of impairment of the immune system and recurrent bronchial infections." (PMID 35273506, 2022). "Muscle and neurogenic anomalies were later described in Vici syndrome patients, and in the last decade recessive mutations in EPG5 were identified as cause of the disease." (PMID 34308255, 2021). "A common missense mutation discovered from studies on two large cohorts of Vici syndrome is a nucleotide mutation at position 1007 of the epg5 gene." (PMID 33674710, 2021). "For example, mutations in EPG5 are associated with Vici syndrome, a multisystem disorder with defective autophagy, agenesis of the corpus callosum, neurodevelopmental delay and neurodegeneration (Online Mendelian Inheritance in Man entry OMIM242840)." (PMID 30348966, 2018). "In 2013, our team linked Vici syndrome to recessive mutations in EPG5 on chromosome 18q, encoding ectopic P-granules autophagy protein 5 (EPG5) with a key role in autophagy in multicellular organisms." (PMID 26917586, 2016). "Studies in EPG5-mutated fibroblasts from humans with Vici syndrome suggest that EPG5 deficiency results in failure of autophagosome-lysosome fusion and, ultimately, impaired cargo delivery to the lysosome." (PMID 26927810, 2016). "Most EPG5 mutations associated with Vici syndrome are truncating with only few missense mutations on record." (PMID 26927810, 2016). "Vici syndrome is due to recessive mutations in EPG5 on chromosome 18q12.3, encoding ectopic P granules protein 5 (EPG5), a key autophagy regulator in higher organisms." (PMID 26927810, 2016). "To date, around 40 EPG5 mutations have been identified in families with Vici syndrome, distributed throughout the entire EPG5 coding sequence without clear genotype-phenotype correlations." (PMID 26927810, 2016). "While biallelic inheritance was thus confirmed in 98% of patients with EPG5-related Vici syndrome, in one case, included because of diagnostic clinical features (Patient 16.1), only one heterozygous but clearly pathogenic EPG5 mutation was identified." (PMID 26917586, 2016). "Vici syndrome is due to recessive mutations in EPG5 on chromosome 18q12.3, organized in 44 exons and encoding ectopic P granules protein 5 (EPG5), a protein of 2579 amino acids." (PMID 26927810, 2016). "EPG5 (originally known as KIAA1632) was initially identified amongst a group of genes found to be mutated in breast cancer tissue before its implication in Vici syndrome in 2013." (PMID 26927810, 2016). "The diagnosis of Vici syndrome is based on the presence of suggestive clinical features and confirmation of recessive EPG5 mutations on diagnostic genetic testing." (PMID 26927810, 2016). "It is currently uncertain if impaired autophagy is the only consequence of EPG5 deficiency, or only the most important expression of a more generalized vesicular trafficking defect in Vici syndrome." (PMID 26927810, 2016). "It remains to be determined whether such aberrant trafficking of the LE/Ly in Epg5 null cells is responsible for the known immunodeficiency in humans with Vici syndrome, which is characterized by mutations in EPG5." (PMID 40742812, 2025). "Patient 1 is a 4-year-old male with an established diagnosis of Vici syndrome due to compound heterozygosity for EPG5 variants NC_000018.10:g.45916107C > A;NM_020964.3:c.3484G > T;NP_066015.2:p.Glu1162Ter and NC_000018.10:g.45944005C > A;NM_020964.3c.1792G > T;NP_066015.2:p.Gly598Cys." (PMID 41312553, 2025). "Mutations in EPG5 were identified as being associated with Vici syndrome." (PMID 40161923, 2025). "EPG5, a less noted protein, was first identified as an autophagy-related gene during clinical genetic analysis, which reported that EPG5 mutation causes a multisystem disorder termed Vici syndrome, characterized by abnormalities in the brain, immune system, and reduced melanin production." (PMID 35008395, 2022).
Vici syndrome (continued). "So far, 40 different private mutations in the EPG5 gene in Vici syndrome have been reported." (PMID 36726976, 2022). "Vici Syndrome is caused by biallelic pathogenic variants in EPG5, resulting in impaired autophagy." (PMID 36204321, 2022). "Another example of dysfunctional Rab7‐mediated signaling in NDD is found in patients with Vici syndrome and recessive variants in the ectopic P‐granules autophagy protein 5 (EPG5) gene, where EPG5 deficiency causes a blockade in autophagosome‐lysosome tethering and deficient Rab7‐mediated signaling." (PMID 35880319, 2022). "EPG5 is a large-sized metazoan protein proposed to serve as a tethering factor to enforce autophagosome–lysosome/late endosome fusion specificity, and its deficiency causes a severe multisystem disorder known as Vici syndrome." (PMID 33674710, 2021). "WIPI3 and WIPI4 may participate in autophagosome-lysosome fusion by promoting lysosomal localization of the protein EPG5, which is mutated in Vici syndrome, as discussed later in this review." (PMID 34308255, 2021). "Likewise, patients with Vici syndrome, a multisystem disorder caused by mutations in the autophagosome-lysosome tethering protein EPG5, have callosal agenesis, developmental delay, microcephaly, and seizures." (PMID 29698489, 2018). "The EPG5 protein has a key role as a regulator of autophagy in multicellular organisms, initially characterized in C. elegans and subsequently confirmed in EPG5-mutated humans with Vici syndrome." (PMID 26927810, 2016). "The observation of histopathological features closely resembling CNM in Vici syndrome, a severe human multisystem disorders due to recessive mutations affecting the key autophagy regulator epg5, provides additional support for a link between the CNMs and the autophagy pathway." (PMID 25566070, 2014). "Vici syndrome (VS), the paradigmatic disorder of defective autophagy characterized by both neurodevelopmental and multisystem features, is caused by recessive variants in EPG5, encoding the ectopic P‐granules 5 autophagy protein with a key role in autophagosome–lysosome fusion." (PMID 41053928, 2025). "In epg5-/- mice, similar autophagic disruptions are observed, including selective neuronal degeneration which partially mirror human Vici syndrome features such as agenesis of the corpus callosum." (PMID 41277110, 2026). "While a similar effect on pancreatic cells has not yet been specifically investigated in mouse models of EPG5 deficiency, further follow-up studies are needed in patients with EPG5-related Vici syndrome and corresponding animal models." (PMID 41312553, 2025). "epg5−/- mice show a clear neurodegenerative phenotype as observed in humans, however this only arises in adulthood, while the majority of Vici syndrome patients present with very early-onset neurodegeneration." (PMID 34130600, 2022). "While essentially a multisystem disorder, neurological aspects are most prominent in EPG5-related Vici syndrome and comprise both neurodevelopmental and neurodegenerative aspects." (PMID 34130600, 2022). "While in both conditions, the primary defect thus likely originates in the lysosome, histopathological features of marked autophagic buildup and variable degrees of exocytosis are identical to what has been observed in EPG5-related Vici syndrome." (PMID 34130600, 2022). "A phenotype common to Vici syndrome patients and Epg5-/- mice is agenesis of the corpus callosum, although the mouse model only partially reproduces the clinical features of the human syndrome." (PMID 34308255, 2021). "Similar structural accumulation is observed in Epg5 knockout mice and tissues from patients with Vici syndrome." (PMID 32528724, 2020). "EPG5-related Vici syndrome emerged as a profoundly severe neurodevelopmental disorder, and our data suggest that acquisition of certain developmental skills virtually excludes EPG5 involvement even if some of the other features are present." (PMID 26917586, 2016).
Vici syndrome (continued). "Considering common features of increased glycogen storage and mitochondrial abnormalities, EPG5-related Vici syndrome also ought to be considered in genetically unresolved ‘glycogen storage’ or ‘mitochondrial’ disorders suspected on histopathological grounds." (PMID 26917586, 2016). "This series includes 50 patients from 30 families with EPG5-related Vici syndrome; 33 patients from 17 families are reported here for the first time." (PMID 26917586, 2016). "Little is known about the physiological cellular interactions of the EPG5 protein, and it remains unclear if impaired autophagy is the only consequence of EPG5 deficiency, or just the most dramatic expression of a more generalized vesicular trafficking defect in patients with Vici syndrome." (PMID 26927810, 2016). "We also obtained natural history data that will be useful for future clinical trials, indicating EPG5-related Vici syndrome as a severe disorder with a markedly reduced life expectancy." (PMID 26917586, 2016). "Our observation of a common occurrence of structural and degenerative changes affecting the same organ in the same patient suggests that EPG5-related Vici syndrome is as much a disorder of embryonic organ development as of normal organ function." (PMID 26917586, 2016). "We conclude that EPG5-related Vici syndrome defines a novel group of neurodevelopmental disorders that should be considered in patients with suggestive features in whom mitochondrial, glycogen, or lysosomal storage disorders have been excluded." (PMID 26917586, 2016). "Chediak-Higashi syndrome also features neuro-ophthalmological similar to those seen in EPG5-related Vici syndrome, indicating that both conditions belong to the same group of syndromic albinism." (PMID 26917586, 2016). "Here we report genetic, clinical, neuroradiological, and neuropathological features of 50 patients from 30 unrelated families with EPG5-related Vici syndrome (including 33 previously unreported cases)." (PMID 26917586, 2016). "Epg5 interacts with Rab7 and LC3 to mediate autophagosome-lysosome fusion in fly, worm, and mammalian cells, and its mutations are linked to Vici syndrome, a severe neurodegenerative disorder in humans." (PMID 41147582, 2025). "At the time of its introduction in 2016, six conditions (EPG5‐related Vici syndrome, WDR45‐related BPAN, SNX14‐related ataxia as well as SPG11‐, ZFYVE26‐, and TECPR2‐related spastic paraplegia) were included with the concept of congenital disorders of autophagy." (PMID 39420677, 2025). "In addition to Vici syndrome, the reduced interaction of EPG5 with LC3 and the downregulation of Rab7 expression have been shown to impair autophagy at the late stage in platelets from human sepsis patients." (PMID 38534345, 2024). "Impaired autophagic flux and accumulation of autophagosomes in EPG5-related Vici syndrome closely resembles the histopathological findings in lysosomal storage disorders such as GM1 gangliosidosis, Niemann-Pick disease type C1 (NPC1), and the neuronal ceroid lipofuscinoses (NCLs)." (PMID 34130600, 2022). "The best-characterized animal model for Vici syndrome is the epg5−/- mouse model." (PMID 34130600, 2022). "A m.10197G>A variant with 4.6% heteroplasmy was detected in a patient with confirmed Vici syndrome due to a homozygous splice variant in EPG5, which was not present in any of the maternal family members." (PMID 34791078, 2022). "Absence of corpus callosum, cataracts, hypopigmentation, cardiomyopathy, immune dysfunction, profound developmental delay, progressive microcephaly, and failure to thrive have a 97% specificity and an 89% sensitivity for a positive EPG5 genetic test in Vici syndrome." (PMID 36726976, 2022). "The clear link between the autophagy pathway and cellular trafficking due to mutations in those genes may thus explain the observed clinical similarities between WMS and EPG5-related Vici syndrome." (PMID 34130600, 2022).